CEACAM5 (CEA cell adhesion molecule 5)
Diseases named in the same sentence as CEACAM5 in open-access papers (continued):
Sharing a sentence is not in itself a finding about the gene and the disease.
lung cancer (240 papers, 1981 to 2026). A malignant neoplasm involving the lung. "CAS cells, predominantly found in tumour regions, expressed SPINK1, CEACAM6 and CEACAM5—genes implicated in tumour proliferation and migration in lung cancer." (PMID 40824728, 2025). "Overall, these results demonstrate the robustness of AKR1B10 and CEACAM5 in the cytologically normal bronchial epithelium in discriminating both the high-risk and lung cancer groups from the low-risk group." (PMID 37760474, 2023). "These include a few markers (e.g. CA-125/MUC-16 and CEACAM5/CEA) that have previously been reported in studies using pre-diagnostic blood samples for lung cancer." (PMID 37264016, 2023). "While CEA (CEACAM5) represents a well-characterized tumor biomarker, the association of other biomarkers with lung cancer varies considerably, with limited evidence of differential expression in early-stage disease." (PMID 26279647, 2015). "CEACAM5 has been shown to be over-expressed in lung cancer and was the 6th ranked gene linked to Lung Neoplasms using our literature ranking approach." (PMID 25374782, 2014). "Similarly, primary EGFR‐mutated lung cancer cells (MGH119) showed higher CEACAM5 and epithelial marker CLDN1 expression but lower mesenchymal marker CDH2 expression than their EGFR‐TKI gefitinib‐resistant counterparts (MGH119GR)." (PMID 40856433, 2025). "Notably, several of the proteins most strongly associated with lung cancer, including CEACAM5, IL6, and SCF, were weakly correlated with other markers and did not have any stable connections with other identified risk markers." (PMID 37264016, 2023). "This suggests that the C allele, showing increased risk for NSCLC may have a role in increasing expression of CEACAM5, which is in concordance with the observed increase in expresion in lung cancers." (PMID 25374782, 2014). "In cancer tissue, CEACAM5 is highly expressed on the membrane of cells in epithelial cancer, including colon cancer, stomach cancer, lung cancer, pancreatic cancer, cervical cancer and others." (PMID 40358697, 2025). "Therapeutic antibodies targeting CEACAM6 and CEACAM5 are under clinical investigation for solid tumours, including CEACAM5‐positive lung cancer." (PMID 40824728, 2025). "We collected 3 pairs of lung cancer samples with different pathological responses to immunotherapy to validate the differential protein expression of marked genes of CEACAM5+ epithelial with western blot and immunohistochemistry." (PMID 41266534, 2025). "For example, we replicated the association of CDCP1 with lung cancer risk reported within the EPIC cohort and also found concordant evidence for risk proteins, such as CEACAM5, identified within up to three years before diagnosis in the INTEGRAL project." (PMID 38750076, 2024). "We identified 28 proteins associated with the risk of lung cancer overall and/or at least one histological subtype that included WFDC2 and CEACAM5 [1.52 (1.39–1.67) and 1.44 (1.33–1.56)]." (PMID 38750076, 2024). "In vitro, NILK-2401 binds dose-dependently to colorectal (3/3), gastric (2/2) and lung carcinoma (2/2) cell lines with different CEACAM5 expression levels." (PMID 38720892, 2024). "In batch 2, CEACAM5 and IDH2 demonstrated identical results in the brushings, and as expected, the low-risk group is significantly different from the lung cancer group." (PMID 37760474, 2023). "First, we explored a large national cancer database for CEACAM5 RNA expression levels in various lung cancers." (PMID 36705924, 2023). "The collective results of this phase I dose-escalation study will inform further studies of tusamitamab ravtansine in patients with solid tumors with CEACAM5 expression, including patients with non–small cell lung cancer." (PMID 37645622, 2023). "The CEACAM5 surface expression was first screened in 7 lung cancer cell lines, 4 pancreatic cancer cell lines, and 3 other cancer cell lines." (PMID 36923424, 2023).
lung cancer (continued). "In lung cancer, the clinical value of CEACAM5 is limited because of its insufficient sensitivity and specificity, but it is often used in combination with other tumor markers." (PMID 31357969, 2019). "Anti-CEACAM5 therapy holds promise for broader applications in lung cancer." (PMID 41266534, 2025). "Although CEACAM5 expression can also be found in gastrointestinal, genitourinary, breast and lung cancers, a recent unbiased surface profiling effort showed a strong enrichment of CEACAM5 expression in NEPC and subsequent in vivo models demonstrated activity of a CEACAM5 ADC in NEPC PDX models." (PMID 38760413, 2024). "An interesting observation was that several of the proteins most strongly associated with lung cancer, including CEACAM5, IL6, and SCF, did not have any stable connections with the identified markers." (PMID 37264016, 2023). "CEACAM5 is a cell surface glycoprotein that is overexpressed in a variety of human tumors, including pancreatic cancers, breast cancers, lung cancer, and neuro-endocrine prostate cancer (NEPC) and has been functionally associated with tumor differentiation, invasion, and metastasis." (PMID 36923424, 2023). "In the univariate analysis, compared to the low-risk group, AKR1B10, ALDH3A1, CEACAM5, and IDH2 are higher than the high-risk or cancer group, i.e., their upregulation discriminates the low-risk group from the high-risk group as well as the lung cancer group." (PMID 37760474, 2023). "No SGM-101 fluorescence, no CEACAM5 staining, and no other immunohistochemical staining were associated with markers of lung malignant neoplasms, including thyroid transcription factor 1 (TTF-1), cytokeratin 5/6 (CK 5/6), and p63 (eFigure 6 in Supplement 2)." (PMID 36705924, 2023). "However, some gastric cancer, pancreatic cancer (PAAD), lung cancer and breast cancer also showed elevated CEACAM5 expression." (PMID 31897235, 2020). "While upregulation of CEACAM5 and CXCL17 seems to have a biological explanation, the underlying mechanism of the lower systemic levels of both important cancer related receptor tyrosine kinases, VEGFR2 and ERBB3, in lung cancer patients, remains elusive." (PMID 31357969, 2019). "In immunohistochemistry experiments, the expression levels of multiple genes, including CHCHD2, CEACAM5, GAPDH, and CD24, were significantly upregulated in lung cancer tissues compared to normal tissues." (PMID 38872167, 2024). "A majority of proteins (23 out of 36) showed stronger odds ratios for late-stage compared with early-stage (stage 1–2) lung cancer, but a clear difference (p-heterogeneity [phet] < 0.05) was only apparent for two proteins (CXL17 and CEACAM5)." (PMID 37264016, 2023). "Given the specificity of the fluorochrome, the ability to readily determine CEACAM5 tumor expression from preoperative biopsies, and the serum detection of glycoprotein, SGM-101 presents an intriguing area to explore in IMI-guided lung cancer resections." (PMID 36705924, 2023). "The level of CEACAM5 (P < 0.001), CNGB1 (P = 0.001), CSTL1 (P = 0.009), RASAL1 (P < 0.001) expression were higher in lung tissues of patients with lung cancer alone than controls." (PMID 33791201, 2021). "CEACAM1, CEA/CEACAM5, and CEACAM6 are cell adhesion molecules (CAMs) of the carcinoembryonic antigen (CEA) family that have been shown to be deregulated in lung cancer and in up to 50% of all human cancers." (PMID 20090913, 2010). "Targets in lung cancer mainly include HER2, HER3, TROP2, MET, CEACAM5, B7-H3 etc." (PMID 41020004, 2025). "It is our routine institutional practice not to perform diagnostic biopsy for patients with lesions concerning for primary lung cancer and unlike the control cohort did not have preoperative CEACAM5 or diagnosis status." (PMID 36705924, 2023). "The diversity of CEACAM5 expression was the highest in the investigated lung cancer specimen; 6/17 (35%) each did express high or no CEACAM5, respectively." (PMID 38087365, 2023).
lung cancer (continued). "CEACAM5-targeted therapies, including CAR-T cells or ADCs, have been developed against lung cancer." (PMID 36923424, 2023). "Unfortunately, total 7 lung cancer cell lines exhibited no CEACAM5 surface expression, so we generated CEACAM5-stably expressing DM4-sensitive (DM4S) NSCLCs, H1299-CEACAM5 and A549- CEACAM5." (PMID 36923424, 2023). "NILK-2301 showed also positive effects on the overall tumor fraction of lung cancer samples, independent of CEACAM5 expression and should be further evaluated alone and in combination with immune checkpoint inhibition." (PMID 38087365, 2023). "In addition, the level of CEACAM5 (P = 0.030), CNGB1 (P = 0.042), CSTL1 (P = 0.046), RASAL1 (P = 0.039), SLC4A3 (P = 0.035) expression were higher in patients with lung cancer coexisting COPD than that in patients with lung cancer alone." (PMID 33791201, 2021). "The level of CEACAM5 (P < 0.001), CNGB1 (P < 0.001), CSTL1 (P < 0.001), RASAL1 (P < 0.001), SLC4A3 (P < 0.001) expression were also increased in lung tissues of patients with lung cancer coexisting COPD compared to controls." (PMID 33791201, 2021). "A recent study investigating non-cancer tissue sections taken from patients with lung cancer identified the clear expression of CEACAM5 as well as CEACAM1 and CEACAM6 family members in this non-cancer tissue." (PMID 28660319, 2017). "We also found that A549 cells expressed significant amounts of non-membrane anchored variants of CEACAM5 and CEACAM6, representing a putative source for the increased CEACAM5/6 serum levels frequently found in lung cancer patients." (PMID 20090913, 2010). "In regard to other ADC targets, carcinoembryonic antigen-related cell adhesion molecule 5 (CEACAM5) is highly expressed in about 25% of lung cancers, and a novel ADC targeting this is tusamitamab ravtansine, comprising a humanized monoclonal antibody and a cytotoxic maytansinoid, DM4." (PMID 38107063, 2023). "The 2023 European Lung Cancer Congress published that the monotherapy of CEACAM5-targeting ADC SAR408701 (Tusamitamab Ravtansine) had showed antitumor activity and safety in patients with CEACAM5-positive non-squamous non-small cell lung cancer who have received multiple treatment regimens." (PMID 39060958, 2024).
breast carcinoma (202 papers, 1979 to 2026). "Gene expression profiling has also revealed that high CEACAM5 expression predicts poor outcomes in estrogen receptor (ER)‐positive breast cancer, while low CEACAM5 expression is linked to poor survival in basal‐like breast cancer." (PMID 40856433, 2025). "Associations between CEACAM5 positivity in breast cancer tissues and patient characteristics (n = 257)." (PMID 31331982, 2019). "High levels of CEACAM5 have been associated with operable early breast cancer." (PMID 31356589, 2019). "Immunohistochemistry analyses have demonstrated that CEACAM5 expression varies among breast cancer subtypes." (PMID 40856433, 2025). "CEACAM5 overexpression has also been reported in other malignant tumours, such as gastric cancer, breast cancer, and pancreatic cancer." (PMID 34663338, 2021). "In survival analysis, using cohort studies of breast cancer, expression of CEACAM5 predicted different clinical outcomes depending on molecular subtypes." (PMID 33196697, 2020). "Assessing sample sets of paired primary breast cancers and corresponding lymph node lesions from a total of 59 patients revealed a high correlation between primary tumor and lymph node with regard to CEACAM5-status." (PMID 33196697, 2020). "To examine the role of CEACAM5 in the process of tumor dissemination of breast cancer cells, we measured the invasive capacity in a Matrigel-coated transwell filter invasion assay using two different breast cancer cell lines." (PMID 33196697, 2020). "To test this, we first immunohistochemically examined CEACAM5 expression patterns of a small sample of 11 pairs of frozen invasive primary breast carcinomas with corresponding lymph node metastases using mAb CB30." (PMID 33196697, 2020). "In total, these data suggest a multifaceted role for CEACAM5 that depends on breast cancer subtype with regard to carcinogenesis." (PMID 33196697, 2020). "Here, we assess CEACAM5 expression in breast cancer subtypes by immunohistochemistry, and compare the expression pattern in primary tumors to corresponding lymph node metastases." (PMID 33196697, 2020). "In our sample of 110 breast carcinomas, 55% were CEACAM5-positive by immunohistochemistry which is in line with several of the previous reports." (PMID 33196697, 2020). "Altogether, our analysis suggests that CEACAM5 plays a context-dependent role in breast cancer that warrants further investigation." (PMID 33196697, 2020). "When examining the consequence of expression of CEACAM5 in breast cancer cell lines in culture assays we found that CEACAM5-expressing cells were less invasive." (PMID 33196697, 2020). "Of the 49 breast carcinomas that were among the Luminal A subtype, 34 (69%) carcinomas were CEACAM5-positive." (PMID 33196697, 2020). "Since then several immunobased assays have been implemented to examine the role of CEACAM5 as a clinically relevant marker in breast cancer." (PMID 33196697, 2020). "To get some insight to the clinical relevance of expression of CEACAM5 in breast cancer, we utilized an online-based tool to draw survival plots of patient groups divided by gene expression levels from breast cancer cohort studies." (PMID 33196697, 2020). "Among breast cancer subtypes, the frequency of CEACAM5-positivity was notably lower in TN carcinomas (24%) compared to other subtypes (> 60%)." (PMID 33196697, 2020). "Here, we examined a repository of 110 cryopreserved primary breast carcinomas by immunohistochemistry to assess the distribution of CEACAM5 in tumor subtypes." (PMID 33196697, 2020). "In order to substantiate these observations, we evaluated a tumor micro array (TMA) consisting of 50 pairs of paraffin-embedded metastatic primary breast carcinomas and corresponding lymph node metastases for expression of CEACAM5." (PMID 33196697, 2020). "This was supported by experimental data showing that CEACAM5-overexpressing breast cancer cells were less invasive." (PMID 33196697, 2020).
breast carcinoma (continued). "When CEACAM5 was overexpressed, MCF7i and MDA-MB-468 breast cancer cells became less invasive than control cell lines where low endogenous levels of CEACAM5 were exhibited." (PMID 33196697, 2020). "IHC staining on a matched tissue set consisting of a primary tumor and a lung metastasis from a patient with breast cancer revealed higher CEACAM5 levels in the lung metastasis relative to the primary breast tumor." (PMID 29736411, 2018). "Vimentin expression was also inversely correlated with CEACAM5 expression in a panel of breast cancer cell lines." (PMID 29736411, 2018). "Among the top five hits, CEACAM5 was the only one whose expression in primary tumors was found to predict poor survival in breast cancer patients." (PMID 29736411, 2018). "Next, CEACAM5 expression was assessed in metastatic lesions and breast tumor tissue obtained from patients with breast cancer." (PMID 29736411, 2018). "High expression of CEACAM5 and CEACAM6 has been associated with a variety of malignancies including breast cancer." (PMID 23285151, 2012). "When we probed lysates of 4 primary mammary tumors we found that only one of the samples showed a specific Col-1 signal at the expected molecular weight of 180 kDa of the human CEACAM5 molecule." (PMID 21436956, 2011). "Anti-human CEACAM5 antibody Col-1, previously being applied for cancer diagnosis in dogs, immunohistochemically reacted to 23 out of 30 canine mammary cancer samples." (PMID 21436956, 2011). "Interestingly, CEACAM5 overexpression has been reported to inhibit invasion in breast cancer cells and block TGF‐β‐mediated EMT." (PMID 40856433, 2025). "Furthermore, the silencing of CEACAM5 expression synergized with tamoxifen-induced growth inhibition in breast cancer cells." (PMID 38851782, 2024). "Besides, JAK1-STAT3 pathway up-regulated the expression of SOX9 and induced CEACAM5 overexpression, thus promoting breast cancer cell invasion." (PMID 38686388, 2024). "In previous studies, we demonstrated that NEO-201 reacts to colon, ovarian, pancreatic, non-small cell lung, head and neck, cervical, uterine and breast cancers expressing tumor-associated variants of CEACAM5 and CEACAM6 but does not react to normal tissues." (PMID 36291783, 2022). "It has also been demonstrated that CEACAM5, CEACAM6, and CEACAM19 are overexpressed in breast cancer and are associated with enhanced tumor invasiveness and metastasis." (PMID 34447411, 2021). "In a search for CEACAM5-specific antibodies that work optimally for immunohistochemistry on cryosectioned breast cancer tissue, we tested three monoclonal antibodies (mAbs): CB30, COL-1 and 1105, all of which have been utilized in previous studies by other groups." (PMID 33196697, 2020). "Early work suggested that CEACAM5 was also often overexpressed in breast cancer." (PMID 33196697, 2020). "Overall, the findings in this study may help improve the understanding of the biological effect of CEACAM5-expression in breast cancer." (PMID 33196697, 2020). "Furthermore, based on preoperative serum levels, two studies have shown that a lower proportion of women with TN breast cancer have elevated CEACAM5 compared to other molecular subtypes." (PMID 33196697, 2020). "Importantly, we found that the distribution of CEACAM5 expression significantly differed among breast cancer subtypes." (PMID 33196697, 2020). "Furthermore, CEACAM5 overproduction reduced expression of mesenchymal markers in breast cancer cells and promoted the outgrowth of metastatic lesions in the lungs of mice." (PMID 29736411, 2018). "CEACAM5 was first described in 1965 as a gastrointestinal oncofetal antigen, but is now known to be overexpressed in a majority of carcinomas, including those of the gastrointestinal tract, the respiratory and genitourinary systems, and breast cancer." (PMID 17201906, 2007).